HGF (hepatocyte growth factor)
Diseases named in the same sentence as HGF in open-access papers (continued):
Sharing a sentence is not in itself a finding about the gene and the disease.
tumor (continued). "Some components of the tumor stroma such as activated cancer-associated pancreatic stellate cells are implicated in neoangiogenesis by activating the c-MET pathway through the release of HGF." (PMID 25483099, 2014). "Furthermore, our previous work has shown that BBC displays a significant relationship with stroma-secreted HGF (also known as scatter factor), a growth factor associated with tumor aggressiveness." (PMID 25072025, 2014). "HGF/Met signaling is frequently implicated in cancer, driving tumor invasiveness and metastasis." (PMID 25534569, 2014). "We have reported that in ApcMin/+ mice, targeted disruption of the Spint1 gene that encodes HAI-1 resulted in significantly increased amounts of tumor formation, whereas activation of HGF/SF in the intestine was enhanced in HAI-1-deficient tumors and non-tumor mucosa." (PMID 25268161, 2014). "Moreover, many other studies have implicated HGF and its receptor, the c-Met proto-oncogene, in tumor progression and metastasis in HCC." (PMID 23723997, 2013). "In addition, elevated serum levels of HGF are significantly associated with advanced tumor metastasis stage and poor survival in HNSCC." (PMID 24287743, 2013). "Thus, not only tumor-secreted mediators, but also HGF mutation or environmental pollutants should be considered as a causal factor for tumorigenesis." (PMID 23296269, 2013). "In addition, high circulating HGF levels are associated with lower survival and development of distant metastasis, and increases in circulating HGF are correlated with tumor size, nodal status, and histological evidence of venous invasion." (PMID 23320110, 2013). "Even in cases of MET mutation, HGF is important for tumor malignancy." (PMID 23296269, 2013). "In addition, MET transcription is induced by environmental cues, such as growth factors secreted by the adjacent stroma, including HGF itself, or by oxygen deficiency, or hypoxia, a frequent occurrence in the rapidly growing tumor tissue." (PMID 22973229, 2012). "HGF/c-Met activation of ®-catenin may account for the discrepancies between gene mutation and protein expression seen in these tumours and this could indicate susceptibility to RTK-targeting agents in the treatment regimen." (PMID 21992464, 2011). "Tumor lines with mutated c-Met or overexpressed c-Met and/or HGF/SF are tumorigenic in vitro and in vivo; and tumor cells transfected with c-Met and HGF/SF are capable of forming tumors with an invasive and metastatic phenotype in the nude mice." (PMID 19939254, 2009). "Moreover, Madin–Darby canine kidney (MDCK) cells expressing exogenous human DESC1 acquire properties associated with tumour growth such as enhanced motility and an increase of tubular forms in a 3D collagen lattice following HGF treatment." (PMID 17579619, 2007). "Tumor-derived Asn acts as a paracrine signal that induces inflammatory cancer-associated fibroblast (iCAF) like activation in hepatic stellate cells (HSCs) and promotes iCAF polarization in primary CAFs, leading to enhanced HGF secretion that further stimulates MET+ tumor cells." (PMID 41861091, 2026). "Similarly, HGF is a potent mitogen that has been linked to tumor cell survival and migration, raising the possibility that its upregulation following TACE may facilitate residual tumor growth." (PMID 40867270, 2025). "Dysregulation of the paracrine HGF/c-Met activation could also provide oncogenesis and tumor progression in several cancers and promote aggressive cellular invasiveness associated with tumor metastasis." (PMID 38817451, 2024). "Thus, for patients with both sensitizing EGFR mutations and extensive tumor-stroma interactions, additionally targeting HGF/MET may restore the response to EGFR TKIs." (PMID 36647832, 2023).
tumor (continued). "The gene MACC1 is a key regulator of the HGF/c-Met pathway and its overexpression is causative for cancer cell proliferation, colony formation, dissemination, migration, and invasiveness in cell culture and for tumorigenesis, tumor progression and metastasis formation in several mouse models." (PMID 35406521, 2022). "Thus, we hypothesized that enhanced HGF production caused by infection may contribute to tumor progression via the activation of the HGF/c-Met signaling pathway." (PMID 32630328, 2020). "Thus, the association between higher postoperative HGF levels and prognosis may differ based on the tumor type (e.g., histological type and expression of c-Met)." (PMID 32630328, 2020). "While HGF provokes a variety of cellular signals that mediate tumor growth and metastasis, DPSCs/HGF may reduce the risk of HGF-induced adverse reactions, because the engrafted DPSCs survive for a short time only and the elevation of HGF levels in the ischemic brain are localized." (PMID 30151417, 2018). "However, in cancer cells, aberrant HGF/c-Met axis activation, which is closely related to c-Met gene mutations, overexpression, and amplification, promotes tumor development and progression by stimulating the PI3K/AKT, Ras/MAPK, JAK/STAT, SRC, Wnt/β-catenin, and other signaling pathways." (PMID 29455668, 2018). "HGF, produced by a large number of tumors, such as carcinomas, soft tissue sarcoma, and hematopoietic malignancies, is implicated in tumor angiogenesis, while its receptor c-met is not only expressed by diverse tumor cells, but also present on the surface of immune cells such as DCs." (PMID 28409322, 2017). "By analyzing the most common tumor microenvironmental cytokines, we observed that basal BCSCs, as well as cancer-associated fibroblasts (CAFs) isolated from a basal cancer sample, secrete hepatocyte growth factor (HGF), stromal cell-derived factor 1 (SDF-1) and osteopontin (OPN) in the medium." (PMID 27494839, 2016). "In addition to CAF, tumor-associated macrophages (TAM) are a major source of HGF in tumor tissues." (PMID 23296269, 2013). "The interplay between angiogenic signaling, including VEGF and HGF, and PD-L1 in tumor creates a synergistic axis where impaired vascular integrity and increased pericyte coverage correlate with increased PD-L1 levels, promoting immune escape." (PMID 41597220, 2026). "IL6/IL6R/STAT3 and HIF1α/ZEB1 pathways induce epithelial to mesenchymal transition (EMT) and CAFs secrete EGF, FGF and HGF for tumour growth." (PMID 41476776, 2026). "In terms of signaling pathways and tumor progression, hepatocyte growth factor (HGF) is a multifunctional growth factor that participates in a variety of physiological and pathological processes." (PMID 40860340, 2025). "In parallel, CAF-released hepatocyte growth factor (HGF) activates c-Met in tumor cells, leading to metabolic rewiring through modulation of glycolytic enzymes such as hexokinase-II and phosphofructokinase, alongside increased MCT1 activity." (PMID 41583435, 2025). "During the early stages of tumor progression, particularly in the atypical hyperplasia stage, HGF is significantly upregulated in the stromal compartment." (PMID 40665092, 2025). "A key protein involved in NSCLC metastasis is hepatocyte growth factor (HGF), which is enriched in exosomes derived from highly metastatic tumor cells." (PMID 40176898, 2025). "Among the CD44v isoforms, CD44v6 plays a pivotal role in cancer progression through binding to HGF, osteopontin, and other key cytokines secreted in the tumor microenvironment." (PMID 41369362, 2025). "Immunofluorescence analysis was conducted to assess the effects of TAS-115, alone or in combination with DOXO, on the c-MET/HGF protein expression in heterotypic tumor spheroids." (PMID 41289612, 2025). "The c-Met/HGF signaling pathway is dysregulated in cancer and correlates with abnormal tumor proliferation and survival, tumor invasion, progression, and metastasis." (PMID 41254996, 2025).
tumor (continued). "Mechanistically, GSC-MSCs exhibited elevated hepatocyte growth factor (HGF) levels and higher expression of genes that are favorable for tumor cell proliferation and migration compared to LC-MSCs." (PMID 40676710, 2025). "In normal epithelial cells, METex14Del activation depends on stimulation by HGF, its high-affinity ligand, and the mutant receptor can promote experimental tumor growth only in humanized mice expressing human HGF." (PMID 41184222, 2025). "This suggests that HGF expression in the microenvironment is important for tumor growth in such patients." (PMID 39980226, 2025). "Platelet-derived extracellular vesicles (PEVs) are also implicated in this process, as they enhance the expression of MMP-9, VEGF, HGF, and IL-8 in tumor cells, further highlighting the importance of platelets in regulating angiogenesis in the tumor context." (PMID 39934930, 2025). "The machinery is used for in vivo knockout and disruption of the HGF gene in HepG2 tumors, resulting in effective apoptosis and necrosis of the tumor tissues." (PMID 40334276, 2025). "AFP positivity functions as a potent negative prognostic indicator, potentially mediated via dysregulated hepatocyte growth factor (HGF)/c-Met signaling pathways that enhance tumor aggressiveness and metastatic potential." (PMID 41517322, 2025). "Given its importance in tumor progression and therapeutic resistance, the HGF/c-MET axis has emerged as a potential target for cancer treatment." (PMID 40304568, 2025). "These subtypes uncovered specific alterations in DNA methylation, transcription, and signaling pathways involved in tumor-stromal cross-talk, e.g., hepatocyte growth factor (HGF), IGF, and SHH." (PMID 40427098, 2025). "Vascular endothelial growth factor (VEGF) and hepatocyte growth factor (HGF) are multifunctional cytokines that stimulate angiogenesis during tumor neovascularization." (PMID 40110197, 2025). "Our method can not only uncover disease-causing genes with abnormal expression in tumor samples such as CD74, HGF, but it can also identify genes with stable expression yet crucial roles in LUSC, such as BRAF, KDM6A, MAP2K1, and TPR." (PMID 40136480, 2025). "For that, we used a model of HGF humanised mice (hHGFki) that has a knock‐in of human HGF permitting to activate the human MET at the surface of the injected human tumour cells." (PMID 39374163, 2025). "MET binds hepatocyte growth factor and plays a role in cell motility, stem-like phenotypes, tumor progression, and dysregulation of cytoskeletal regulation of nuclear shape." (PMID 39416100, 2025). "Cytokines such as HGF derived from the tumor microenvironment, upregulate CD44v6 expression in the CSCs via activation of the Wnt/β-catenin signaling pathway, thereby promoting migration and metastasis." (PMID 41369362, 2025). "Baseline hepatocyte growth factor (HGF) and basic fibroblast growth factor (bFGF) expression was significantly higher in the tumor-bearing mice compared to the tumor-free controls." (PMID 39857982, 2025). "In contrast, in NSGhHGF H3122 xenografts, capmatinib substantially enhanced the magnitude of tumor regression and delayed the relapse, supporting the relevance of the HGF-cMET axis for stroma-mediated resistance in vivo." (PMID 40313737, 2025). "Microenvironmental factors from tumor or stromal cells such as tumor-associated macrophages (TAMs), CAFs, including fibroblast growth factors (FGF), TGF-β, EGF, and hepatocyte growth factor (HGF), contribute to cadherin switching." (PMID 40399946, 2025). "By targeting both VEGF and HGF simultaneously, the tumor immune microenvironment (TIME) can be more effectively reshaped to enhance the immune system’s response to tumors." (PMID 40110197, 2025). "NK4 not only negatively regulates the HGF/c-Met signaling pathway but also inhibits tumor angiogenesis independently of the HGF/c-Met pathway." (PMID 40823073, 2025).
tumor (continued). "The knockdown of CD74 or SUB1 suppresses tumor growth, and HGF has shown potential as a therapeutic target due to its role in fibrosis reversal and lung repair." (PMID 40136480, 2025). "Unexpectedly, this effect was detected in both xenograft tumor models, indicating the action of HGF-independent SMR mechanism(s) that overshadow the effects of the HGF-cMET axis." (PMID 40313737, 2025). "Studies have shown that NK4, an HGF antagonist, inhibits HGF/c-Met-induced tumor growth, metastasis, and invasion antagonism ultimately leading to apoptosis." (PMID 40823073, 2025). "The lack of protection against crizotinib suggested mediation by the well-established bypass signaling mechanism, activation of cMET expressed by tumor cells by hepatocyte growth factor (HGF), produced by CAFs." (PMID 40313737, 2025). "Chemokine–receptor interactions, such as the CXCL12/CXCR4 and HGF/c-Met axes, play central roles in guiding NSCs to tumor sites." (PMID 41264121, 2025). "Our study also identified enhanced EGF, MK, TWEAK, and HGF signaling between high-glycan-score tumor cells and others." (PMID 40861802, 2025). "This suggests that HGF expression in the tumor microenvironment is important for tumor growth in patient harboring such mutations." (PMID 39980226, 2025). "Hepatocyte growth factor (HGF) is a key mitogen involved in liver regeneration, tumor cell survival, and metastasis." (PMID 40867270, 2025). "It is demonstrated that lactate stabilized NF-κB within CAFs, prompting the secretion of tumor-promoting HGF, which induced TKIs resistance in tumor cells." (PMID 39934144, 2025). "CAFs are known to influence tumor cell behavior through pathways such as those elicited by e.g. IL-6, HGF/MET, IFNβ1 and certain microRNAs." (PMID 40042717, 2025). "HGF/c-MET signaling fosters the transition of TAMs from the M1 phenotype (anti-tumor, pro-inflammatory) to the M2 phenotype (pro-tumor, immunosuppressive)." (PMID 40281554, 2025). "In our study, we have identified that HRH2 and HGF were mainly expressed in CAFs within the CCA tumor microenvironment." (PMID 41048570, 2025). "HGF is secreted into the tumor microenvironment, where it binds to the MET proto-oncogene/receptor tyrosine kinase receptor on cancer cells to activate MET signaling." (PMID 40723207, 2025). "For instance, CAFs directly enhance tumor cell survival and growth by secreting hepatocyte growth factor (HGF) and other growth factors." (PMID 39858465, 2025). "The intricate interactions between MET and HGF complicate the tumor microenvironment, establishing MET as a vital target for therapeutic intervention in GBM." (PMID 40332008, 2025). "iCAFs can directly interact with tumor cells through secreting hepatocyte growth factor (HGF), thereby enhancing ICC growth." (PMID 40248695, 2025). "The c-Met signaling pathway, initiated by its ligand HGF, engages multiple signaling pathways within tumor cells." (PMID 39891818, 2025). "To quantitatively assess the impact of stroma proximity on tumor cell proliferation and to evaluate the relative contribution of the HGF-cMET axis, we took advantage of our digital pathology/spatial analysis pipeline." (PMID 40313737, 2025). "Cancer-associated fibroblasts and macrophages within the tumor stroma release several growth factors that induce the EMT, such as TGFβ1, PDGF, EGF, and HGF." (PMID 39941895, 2025). "Hepatocyte growth factor (HGF) receptor tyrosine kinase c-Met is another important modulator of tumor angiogenesis, invasion, and metastasis." (PMID 41471364, 2025). "Whereas hHGF expression had no discernable impact on the baseline tumor growth, it prevented tumor regression in response to alectinib, indicating that the HGF-cMET axis represents a strong resistance mechanism." (PMID 40313737, 2025).
tumor (continued). "The stronger effect on EGF-induced phosphorylation resulted from blockade of ligand binding and receptor dimerization by the dual epitope EGFR arm as anticipated, while the avidity effect maintained a strong HGF blockade in the tumor cells." (PMID 40452841, 2025). "Multiple signaling pathways, including VEGF, EGF, FGF, and HGF, play pivotal roles in endothelial tube formation and angiogenesis within tumor tissues, contributing to the heterogeneity of blood vessel structures observed in cancer." (PMID 40371330, 2025). "NB cells can both secrete HGF and express MET, which indicates an autocrine loop, and hepatocyte growth factor (HGF) stimulated NB tumour angiogenesis in chick embryos." (PMID 41511287, 2025). "By encouraging cell adhesion and inducing the production of VEGF and IL-8, hepatocyte growth factor (HGF) also aids in the remodeling of the tumor microenvironment." (PMID 41283276, 2025). "Previous studies have shown that neutrophils promote tumor invasion, metastasis, and angiogenesis through the release of tumor suppression factors, hepatocyte growth factor, neutrophil elastase, and matrix metalloproteins." (PMID 40047078, 2025). "For instance, cancer-associated fibroblasts (CAFs) have been shown to secrete hepatocyte growth factor (HGF), which activates MET signaling in drug-tolerant tumor cells." (PMID 40894234, 2025). "When HGF levels increase in the tumor microenvironment, tumor-infiltrating macrophages are more likely to transition into the immunosuppressive M2-polarized phenotype." (PMID 40136462, 2025). "The involvement of the c-Met/HGF signaling pathway as a central effector mechanism in tumor progression, metastasis, and resistance to anticancer therapy makes it an attractive target for cancer treatment." (PMID 40547482, 2025). "HGF not only promotes the proliferation and survival of tumor cells but also increases angiogenesis and immunosuppression through interactions with the microenvironment." (PMID 40110197, 2025). "HGF exerts its effects through binding to the tyrosine kinase receptor Met, involved in tumor progression, including iCCA." (PMID 40723336, 2025). "In this context, HCC cells stimulate neutrophil-mediated hepatocyte growth factor (HGF) production through GM-CSF, thereby enhancing tumor metastasis via the HGF/c-Met axis." (PMID 40868256, 2025). "Specifically, the HGF signaling pathway was observed to have a significant effect on the interaction between fibroblasts and malignant tumor cells." (PMID 40874228, 2025). "Additional research has indicated that CAFs in HCC enhance tumor-initiating cell characteristics and therapeutic resistance by releasing HGF and IL-6, which activate the FRA1 and Notch signaling pathways, respectively." (PMID 40755769, 2025). "In vivo studies have demonstrated that blocking the HGF-MET axis can resensitize tumor cells to EGFR inhibitors and suppress relapse in lung cancer models." (PMID 40894234, 2025). "Genetic alterations (mutations, amplifications, etc.)or c-MET overexpression drive aberrant MET/HGF signaling, promoting tumor initiation, metastasis, and drug resistance across cancers." (PMID 41353695, 2025). "The study demonstrated that LA480 significantly reduced the number of c-Met receptors on the cell surface by blocking the interaction between HGF and the c-Met receptor and effectively decreased total and phosphorylated c-Met levels within tumour cells." (PMID 40599602, 2025). "The dependence of tumor formation in vivo on HGF has been demonstrated using human 16HBE METex14Del cells, which induce tumor growth only when xenografted in HGF-humanized mice." (PMID 41184222, 2025). "Palbociclib, when combined with MEK and OxPhos inhibitors, exhibited tumor-suppressing efficacy, and in another study, abemaciclib and a hepatocyte growth factor inhibitor synergistically inhibited tumor growth in xenografts." (PMID 39598629, 2024).